TLR4 (toll like receptor 4)
Diseases named in the same sentence as TLR4 in open-access papers (continued):
Sharing a sentence is not in itself a finding about the gene and the disease.
melanoma (continued). "In melanoma, interplay between TLR4 and STAT3 has never been reported." (PMID 32312954, 2020). "This knowledge might then be proposed for the potential of using TLR4 in the prediction of PTX response; and targeting the PTX-TLR4 mediated signaling pathway in cancer cells by CpdA could then be a challenge to alleviate PTX resistance in triple-negative BCA and melanoma." (PMID 29486738, 2018). "PTX could markedly induce TLR4 expression in both MDA-MB-231 BCA and MDA-MB-435 melanoma cell lines having a basal level of TLR4 whereas no significant induction in TLR4-transient knockdown cells occurred." (PMID 29486738, 2018). "Thus, prophylactic, but not therapeutic, administration of the TLR4/9 agonist complex attenuated the pulmonary metastasis of B16 melanoma cells." (PMID 21931823, 2011). "On the other hand, our studies indicate that therapeutic treatment of mice with the TLR4/9 agonist complex after inoculation of B16F10 melanoma cells can not reverses tumor cell-induced STAT3 activation, IL-10 expression, and autophagy suppression in the lung tissues." (PMID 21931823, 2011). "Notably, melanoma cells can express receptors for calprotectin, including RAGE (Receptor for Advanced Glycation End-Products), EMMPRIN (Extracellular Matrix Metalloproteinase Inducer, also known as Basigin or CD147), TLR4 (Toll-like receptor 4), and MCAM (Melanoma Cell Adhesion Molecule, CD146)." (PMID 40869349, 2025). "Furthermore, addition of the TLR4 agonist LPS did not affect melanoma clustering." (PMID 39284707, 2024). "TLR4 plays an important role in melanoma as well, because it interacts with TRIM44, a negative prognostic factor in melanoma." (PMID 33980826, 2021). "Renal infiltration of inflammatory cells was also attenuated, with fewer F4/80-positive macrophages and downregulation of monocyte chemoattractant protein-1, toll-like receptor 4, NF kappa-light-chain-enhancer of activated B cells (NF-κB), CD45, and absent in melanoma 2 inflammasome." (PMID 40875507, 2025). "In melanoma, TLR5 is not as well studied as TLR2 or TLR4, but evidence suggests that many cell lines express TLR5 to varying degrees, and therefore, innate and adaptive immunity could be activated by TPV/Δ2L/Δ66R/FliC infections in melanoma cells." (PMID 37628585, 2023). "Whether parthenolide affects both TLR4 and STAT3 in melanoma has not been reported." (PMID 32312954, 2020). "In pilot studies, we have found that inhibitors of IKK (BMS-345541), JNK (SP600125) and TLR4 (TAK-242), but not inhibitors of ERK (U0126) and p38 (SB203580), block LPS-induced STAT3 activation, suggesting that IKK and JNK are involved in TLR4-signaling-mediated STAT3 activation in melanoma." (PMID 32312954, 2020).
myocardial infarction (146 papers, 2007 to 2025). Gross necrosis of the myocardium, as a result of interruption of the blood supply to the area, as in coronary thrombosis. "The main TLRs expressed in myocardial cells include TLR2, TLR3, and TLR410, wherein TLR4 is involved in myocardial injury caused by myocardial infarction." (PMID 38159178, 2024). "TLR4 deficiency has previously been shown to cause less cardiac hypertrophy after myocardial infarction (MI) or pressure overload induced by transverse aortic constriction, but the studies did not address physiologic cardiac function in vivo." (PMID 38140398, 2023). "TLR4 activation on platelets by the virus (viraemia) or DAMPs increases the risk of thrombosis, manifesting in the form of myocardial infarctions and embolisms." (PMID 33505220, 2021). "Recent investigations have demonstrated that TLR4 deficient mice have a decreased infarct size and suppressed inflammation; they also exhibit attenuated adverse remodeling following myocardial infarction." (PMID 32751587, 2020). "Other case-control candidate genes have identified an association between the TLR4 polymorphism and acute myocardial infarction, with a reduced incidence of cardiovascular events in the 299GLy allele." (PMID 27795867, 2016). "Various studies have shown that TLR4-deficient mice have lesser myocardial infarct size than wild-type control animals." (PMID 25692136, 2015). "Similar to TLR2, TLR4-deficient mice show after myocardial infarction enhanced LV function and improved remodeling leading to significantly increased survival of TLR4-deficient mice." (PMID 24611063, 2014). "In the heart, TLR4 deficiency afforded protection against left ventricular hypertrophy and cardiac fibrosis after experimental myocardial infarction." (PMID 24842252, 2014). "We previously demonstrated that enhanced central sympathetic outflow is associated with brain toll-like receptor 4 (TLR4) probably mediated by brain angiotensin II type 1 receptor in mice with myocardial infarction (MI)-induced heart failure." (PMID 23874864, 2013). "One study examined the TLR4 SNP A896G (D299C), associated with decreased LPS stimulated cytokine synthesis, in subjects with acute myocardial infarction (AMI), young people and centenarians." (PMID 23391127, 2013). "In a mouse model of myocardial infarction, TLR4 deficiency resulted in less tissue damage and cardioprotection." (PMID 22577589, 2012). "There is a growing body of evidence linking TLRs, particularly TLR2 and TLR4, to the deleterious inflammatory effects seen in ischemia/reperfusion injury associated with trauma, stroke, myocardial infarction, and solid organ transplantation." (PMID 20628516, 2010). "Pretreatment of animals with pharmacologic inhibitors of the PI3K/Akt signaling pathway, including either wortmannin or Ly294002, abrogated the observed reduction of myocardial infarct (MI) size in TLR4 deficient animals." (PMID 20676278, 2009). "A review published in 2006 summarized direct evidence of TLR4 involvement in vascular injury, showing that TLR4-deficient mice exhibit larger myocardial infarction areas after coronary artery ligation and reperfusion, and TLR4 participates in lipid metabolism and inflammation." (PMID 40103596, 2025). "Actually, TLR4 deficiency has been found to reduce myocardial infarction size." (PMID 34449561, 2021). "TLR4-deficient mice experienced reduced myocardial infarct sizes after myocardial I/R injuries that were mediated by the reduced activity of inflammatory signaling pathways, such as the accumulation of polymorphonuclear neutrophils and the activation of oxidative stress." (PMID 32149124, 2020). "Interestingly, population genetics studies have initially suggested that the hypomorphic TLR-4 allele, leading to a blunted inflammatory activation, Arg299Gly was shown to be associated with the reduced risk of myocardial infarction." (PMID 31089324, 2019).
myocardial infarction (continued). "Therefore, we investigated age associated blood pressure increase in a large clinical cohort of patient with CAD or myocardial infarction in relation the functional TLR4 single nucleotide polymorphism rs 4986790." (PMID 26015800, 2015). "Other studies have suggested that smaller myocardial infarctions in TLR4-deficient mice can be attributed to reduced neutrophil infiltration and NF-κB activation followed by decrease in the levels of the inflammatory cytokines IL-1β and IL-6 as well as of monocyte chemotactic factor-1." (PMID 25692136, 2015). "Other studies, which deal with functional polymorphisms in toll-like receptor 4 could show on the one hand a worse outcome in acute ischemic stroke patients and were associated with myocardial infarction." (PMID 26435700, 2015). "TLR4 deficiency resulted in a moderate reduction in myocardial infarct size." (PMID 25823011, 2015). "Furthermore, the decreased myocardial infarction in TLR4-deficient mice was associated with attenuated myocardial inflammation as evidenced by fewer neutrophil infiltration, less lipid peroxides production, and less complement 3 deposition in the heart." (PMID 21977329, 2011). "Alteration in the inflammatory response to myocardial infarction may account for the observed discrepancy between infarct size and cardiac function for the TLR4 deficient mice." (PMID 17592640, 2007). "Also, in myocardial infarction (MI), the release of endogenous damage-associated molecular patterns (DAMPs) from necrotic cardiac myocytes triggers TLR4 activation, leading to the increased expression of pro-inflammatory cytokines, contributing to additional myocardial damage." (PMID 38790263, 2024). "TLR4 has been associated with various cardiac conditions, including myocardial infarction (MI), ischemia-reperfusion injury (I/R damage), heart failure, myocarditis, aortic valve disease, atherosclerosis, hypertension, and myocardial inflammation." (PMID 37900069, 2023). "Therefore, our results suggest that TLR4 activation in CFs could be another effective strategy to prevent excessive cell death and improve the mechanisms associated with wound repair after myocardial infarction." (PMID 34169098, 2021). "Early studies revealed that TLR4 expression increases in cardiomyocytes during myocardial infarction-induced HF, promoting inflammatory responses and exacerbating HF." (PMID 40640887, 2025). "In a myocardial infarction model, RvD1 pretreatment significantly decreased TLR4 protein expression." (PMID 41463049, 2025). "TLR4 is emerging as a potential biomarker for new-onset AF following acute myocardial infarction, with significantly increased levels observed in patients experiencing new-onset AF compared to healthy controls and those with myocardial infarction alone." (PMID 41357167, 2025). "The expression of TLR4 was significantly reduced in all examined myocardial regions following myocardial infarction compared to the control group." (PMID 41291022, 2025). "TLR4 is a well-known receptor that plays a significant role in mediating maladaptive remodeling and impairing cardiac function following myocardial infarction." (PMID 38791147, 2024). "Previous research demonstrated that suppression of TLR4 protected experimental rats from left ventricular dysfunction and cardiac fibrosis following myocardial infarction." (PMID 39290498, 2024). "TLR4 deficiency, TLR4 antagonist or MyD88 deficiency significantly reduced myocardial IRI, decreased myocardial infarction and improved cardiac function after myocardial IRI." (PMID 39091500, 2024). "TLR4 also affects myocardial infarction (MI) by mediating inflammatory responses through damage-associated molecular patterns from necrotic cardiac cells." (PMID 38790263, 2024). "The inflammatory response during myocardial infarction is regulated by several inflammatory markers, including IL-1β, iNOS, NF-κB, and TLR4." (PMID 39211776, 2024).
myocardial infarction (continued). "Following a myocardial infarction (heart attack), TLR4 signaling is involved in the tissue damage in the heart." (PMID 39453113, 2024). "TLR4 has been shown to be involved in sterile inflammation reactions such as ischaemia-reperfusion injury in myocardial infarction, hepatic, renal, and intestinal ischaemia." (PMID 37251076, 2023). "A previous study has shown that SPI1 upregulation activated the TLR4/NFκB axis and aggravated myocardial infarction." (PMID 36675183, 2023). "A recent experimental study has reported that monocyte TLR4 expression is upregulated in patients with heart failure after acute myocardial infarction." (PMID 37239362, 2023). "A previous in vivo study revealed that RGZ attenuates apoptosis by inhibiting the TLR4/NF-κB signaling pathway in acute myocardial infarction." (PMID 36114448, 2022). "Myocardial infarction induced local TLR4 expression, and upregulated TLR4 in cardiomyocytes that exacerbated heart failure." (PMID 33996944, 2021). "Elevated expression and activity of CD14, TLR2, and TLR4 correlate with advanced atherosclerotic lesions, followed by plaque rupture and myocardial infarction." (PMID 34829669, 2021). "For instance, Nicorandil suppresses TLR4/MyD88/NF-κB/NLRP3 axis to alleviate pyroptosis in rats with myocardial infarction." (PMID 34595225, 2021). "On the other hand, the microenvironment in the failing heart or myocardial infarct promoted a pro-inflammatory phenotype in both resident and transplanted mouse MSCs via TLR4 activation." (PMID 34831203, 2021). "TLR4/MyD88 was shown to activate the nuclear factor-kappa B (NF-κB) inflammatory pathway in enteritis, promote myocardial infarction and induce acute pneumonia." (PMID 34589510, 2021). "While the role of TLR4 in the irradiated heart is not yet fully understood, prior studies have shown a role for TLR4 in myocardial inflammation due to myocardial infarction, myocarditis, and in heart failure." (PMID 34029348, 2021). "TLR4/MyD88‐NF‐κB pathway is involved in the process of DCs maturation and inflammatory response in the development and progression of myocardial infarction with concurrent hyperlipidemia." (PMID 32073735, 2020). "Meanwhile, Tenascin-C is a TLR4 ligand that promotes polarization of M1, but inhibits M2 macrophage through TLR4, thereby accelerating adverse ventricular remodeling after myocardial infarction." (PMID 33324685, 2020). "TLR4 also contributes to the development of cardiac remodeling following pressure overload, myocardial infarction, angiotensin II, or ISO infusion in vivo." (PMID 31440160, 2019). "We investigated 2679 patients with myocardial infarction stratified by age and genotype of the functional TLR4 SNP rs4986790 (Asp299Gly)." (PMID 26015800, 2015). "In summary, our data indicate for this large cohort of patients with myocardial infarction that carriers of the TLR4 SNP rs4986790 starting from the age of 70 years have a lower SBP and pulse pressure." (PMID 26015800, 2015). "TLR4 mediates postinfarct maladaptive LV remodeling and impairs cardiac function after myocardial infarction probably via inflammatory cytokine production and matrix degradation." (PMID 26030867, 2015). "We investigated the human TLR4 SNP rs4986790 (Asp299Gly; 896 A/G) in 2679 patients with history of myocardial infarction." (PMID 26015800, 2015). "Using a temporary left anterior descending (LAD) artery occlusion model, Oyama and colleagues first observed reduced myocardial infarct size in 2 distinct strains of mice that lack functional TLR4 signaling." (PMID 20676278, 2009). "Evidence for a deleterious role of visfatin was presented in a recent study in which a visfatin-neutralizing antibody reduced remodelling and improved cardiac function in rats subjected to a sustained 4-week myocardial infarction via inhibition of the visfatin/TLR4 inflammatory cascade." (PMID 41515891, 2025).
myocardial infarction (continued). "These preliminary experimental data showed that the high levels of TNF-α, TLR4, NF-κB, and ROS might affect the formation of collaterals in myocardial infarction mice." (PMID 41278503, 2025). "Studies have shown that editing the TLR4 gene of human bone marrow mesenchymal stem cells makes them lose the ability of inflammatory response, and injecting the edited cells into the myocardial infarction area of mice with myocardial infarction." (PMID 40933041, 2025). "For example, CTRP1-deficient mice exhibited improved survival, reduced oxidative stress, and reduced inflammation following induction of myocardial infarction by suppressing macrophage activation through enhancing interaction between the adiponectin AdipoR1 and TLR4." (PMID 41515891, 2025). "SPI1 upregulation reportedly stimulated the TLR4/NFκB axis and aggravated myocardial infarction." (PMID 39145311, 2024). "Recent studies have indicated that the primary mechanisms by which TLR4/NF-kB exacerbates myocardial infarction encompass inflammation, oxidative stress, and pyroptosis—an inflammatory form of cell death that governs cardiomyocyte loss post-myocardial infarction—as well as apoptosis." (PMID 38541800, 2024). "Studies have shown that TLR4 activation-mediated myocardial leukocyte infiltration results in oxidative stress and the release of cytokines, leading to cardiovascular diseases such as myocarditis, myocardial infarction, and heart failure." (PMID 36749400, 2023). "Limiting I/R injury-induced TLR4 expression and blocking TLR4-mediated myocardial inflammation, apoptosis and autophagy can confer protection against myocardial I/R injury, which may reduce I/R injury-induced myocardial infarction." (PMID 36835281, 2023). "Importantly, S100A8/A9 binding to TLR-4 has been shown to have a cardio-depressant effect in myocardial infarction by direct inhibition of mitochondrial function in cardiomyocytes." (PMID 37773186, 2023). "Similarly, suppressed EGR1 expression is capable of disrupting hypoxia-induced TLR4/NF-κB signaling pathway activation, which can facilitate acute myocardial infarction-induced myocardial damage." (PMID 35126807, 2022). "Based on the inflammatory and fibrotic markers commonly observed in response to myocardial infarction and development of heart failure, we assessed the expression of mRNA for Tnfa, Il1b,Il6, Il18, Ccl2, Ccl3, Cxcl1, Cxcl2, Col1a1, Col3a1, Postn, and Tlr4 at 1 and 3 months." (PMID 35411847, 2022). "Expressions of TLR2, TLR3, and TLR4 were demonstrated in atherosclerotic lesions and led to the development of the atherosclerotic lesions, atherosclerotic arterial occlusion, and acute myocardial infarction." (PMID 35425840, 2022). "Consistent with previous findings, in a model of myocardial infarction MD1 depletion resulted in elevation of MI-induced fibrosis, inflammation and electrical remodeling via upregulation of TLR4/CaMKII signaling that was linked to increased vulnerability to ventricular arrhythmias." (PMID 35237675, 2022). "Inhibition of TLR2 or TLR4 can reduce myocardial infarction area and inhibit myocardial remodeling." (PMID 36407421, 2022). "Increasing evidence suggests that inhibition of the TLR4/MyD88/NF-κB/NLRP3 inflammasome pathway may reduce myocardial infarction-induced pyroptosis." (PMID 34595225, 2021). "In in vivo models of myocardial infarction, toll-like receptor 4 (TLR4) activation has been reported as a cardioprotector; however, it remains unknown whether TLR4 activation can prevent CF death triggered by simulated I/R (sI/R)." (PMID 34169098, 2021). "And finally, supporting the well‐established phenomenon that HSP60 binds to TLR4 a study showed that TLR4 in cardiomyocytes could aggravate HF by engaging in inflammatory processes in cases of long‐term myocardial infarction." (PMID 32808366, 2021).